TNF (tumor necrosis factor)
Diseases named in the same sentence as TNF in open-access papers (continued):
Sharing a sentence is not in itself a finding about the gene and the disease.
myeloma (continued). "Myeloma cells adhere to the stromal cells and induce secretion of OAFs including interleukin (IL)-6, IL-1, tumor necrosis factor (TNF), IL-11, macrophage inflammatory protein-1α (MIP-1α), hepatocyte growth factor (HGF), parathyroid hormone-related peptide (PTHrP), and others." (PMID 18577267, 2008). "In addition, bone marrow stromal cells surrounding multiple myeloma display noticeably increased production of osteoclastogenic cytokines, including macrophage colony-stimulating factor (M-CSF), tumor necrosis factor-α (TNF-α), IL-6, IL-11, and IL-1β." (PMID 38683225, 2024). "Considering that SELENOW is highly expressed in multiple myeloma and that it promotes osteoclast differentiation, we analyzed the molecular mechanisms underlying SELENOW upregulation in multiple myeloma with an increase in circulating osteoclastogenic factors, including M-CSF, RANKL, IL1β, and TNFα." (PMID 38683225, 2024). "In line with this, myeloma-associated non-canonical genomic aberrations may reinforce pro-survival TNF-mediated NF-κB activity through autoregulatory RelB control and thereby exacerbate the disease." (PMID 33917839, 2021). "Within myeloma niche, after interaction with BM-derived mesenchymal stromal cells, TAMs acquire a secretory profile characterized by a great production of IL-6 and IL-10 and poor production of IL-12 and TNF-α, providing a suitable milieu for myeloma plasma cell growth." (PMID 33194767, 2020). "Interestingly, TNFα levels decrease with thalidomide treatment which may be a result of downstream effects of the drug’s immunomodulatory effects on bone marrow myeloma cells." (PMID 33634031, 2020). "However, it was reported that treatment with thalidomide and its analog actually increased the number of Tregs in patients with multiple myeloma (MM), which may be attributable to the elevated serum levels of TNF after treatment." (PMID 29632537, 2018). "Interestingly, the anti-SLAMF7 antibody-elotuzumab has been approved for use by Food and Drug Administration (FDA), and enhances natural killer cell activation and cancer cell killing through interleukin-2 and TNF-α pathways, significantly improving progression-free survival of multiple myeloma." (PMID 28099903, 2017). "We next highlighted the ways in which BMAT may support MM, for example, through bioactive lipids (as a fuel source, signaling molecule, and a substrate for lipid peroxidation), and myeloma-supportive adipokines (e.g., IL-6, TNFα, MCP-1, PAI-1, IL-6, resistin, and leptin)." (PMID 27379019, 2016). "Therefore, we determined whether coculturing 5TGM1-ΔF cells with 14M1 BMSCs (isolated from a 5T mouse myeloma) protected them from TNF-α-induced apoptosis." (PMID 26009993, 2015). "A recent clinical study has shown that the CD14+ monocytes from multiple myeloma patients could be induced to differentiate into functional DCs by culturing them with the cytokine cocktail consisting of GM-CSF, IL-4, IL-6, TNF-α and IL-1β for use in cancer immunotherapy." (PMID 18533025, 2008). "In a clinical study involving eight patients with refractory/relapsed multiple myeloma (R/R MM) who received BCMA CAR-T cell infusion, TNF-α levels significantly increased during CRS episodes." (PMID 40536724, 2025). "Multiple myeloma patients were found to produce more osteoclastogenic factors (M-CSF, RANKL, IL1β, and TNFα) than healthy individuals." (PMID 38683225, 2024). "For example, in multiple myeloma (MM) cells, IL-6, IGF-1, SDF-1α, tumor necrosis factor-α (TNF-α), and VEGF can promote tumor cell proliferation through the MEK/p42/p44/MAPK signaling cascade." (PMID 38672455, 2024). "Autocrine TNF-α/MCP-1/TNF-R2 signaling further enhances trans-endothelial migration of MM cell lines and primary myeloma samples." (PMID 37744361, 2023). "Cytokines tumor necrosis factor (TNF)-α and interleukin (IL)-6, for example, are provided by the niche and can induce proliferation of myeloma cells, creating a tumor-supportive microenvironment." (PMID 37081258, 2023).
myeloma (continued). "In this manuscript, we have shown that CAR-T cells generated with AW-LVs exhibit a milder secretion of TNF-α and IFN-ɣ after tumor cells encounter, which agrees with the low-density CAR’s results against multiple myeloma." (PMID 35694446, 2022). "The other parameters in disease activity and cytokine involved in the pathogenesis of myeloma were IL-6, VEGF, TNF- α, CRP, and LDH." (PMID 35919637, 2022). "Interleukin 6 (IL-6), vascular endothelial growth factor (VEGF), tumor necrosis factor-alpha (TNF-α), C-reactive protein (CRP), and lactate dehydrogenase (LDH) were also involved in the pathogenesis of myeloma." (PMID 35919637, 2022). "Mechanistically, the pro-inflammatory cytokines IL-6 and tumor necrosis factor alpha (TNFα) secreted by CD169+TAMs, increase vascular leakage and downregulate CD138-mediated cell adhesion; thus, driving myeloma intravasation." (PMID 35847862, 2022). "The immune suppressive myeloma microenvironment has elevated IL-10 and TGF-beta, and was associated with decreased expression of NK activating receptors, TNF and IFN-γ secretion, and impaired NK cytotoxicity toward myeloma." (PMID 33746969, 2021). "In multiple myeloma cells, transcriptional regulation of TRAIL is often triggered by a TNF-α dependent pathway." (PMID 33321722, 2020). "This dual Janus-like role of TNFα has long been known; examples are the CHX-induced degradation of the anti-apoptotic factor cFLIP and the use of NFκB inhibitors in multiple myeloma cells, which enables the activation of programmed cell death by TNFα." (PMID 30875877, 2019). "Studies also show that bone resorption induced by IL-1 and TNF is mediated by p38 MAP kinase and that p38 activity enhances osteoclast maturation and bone resorption in myeloma." (PMID 30791472, 2019). "Highly sensitive and accurate binding studies with a Gaussia princeps luciferase fusion protein of a TNFR1-specific TNF mutant and qPCR analysis revealed that TNFR1 expression in myeloma cell lines correlated with high TNF/MLN4924 sensitivity." (PMID 31406107, 2019). "B cell maturation antigen (BCMA), a plasma cell surface antigen and member of the tumor necrosis factor (TNF) receptor superfamily, is an attractive target for immunotherapy of multiple myeloma due to its high prevalence on malignant plasma cells." (PMID 29899820, 2018). "PIs suppress the production of cytokines including interleukin-6 (IL-6), insulin-like growth factor 1 (IGF-1), and tumor necrosis factor α (TNFα), which can affect MSC and myeloma cell interactions." (PMID 29765356, 2018). "At the same time, multiple myeloma cells also produce factors that stimulate osteoclastogenesis including RANK-L, IL-6, MIP-1 alpha, and TNF-alpha." (PMID 29867053, 2018). "Increased levels of key cytokines have also been shown to progressively increase from controls to smouldering myeloma to multiple myeloma including CXCL8 (IL-8), IL-10, TNFα, IL6 and IFNγ." (PMID 28389623, 2017). "In myeloma patients, diverse angiogenic factors such as VEGF, endoglin, TNF-alpha, HGF, FGF, endostatin, thrombospondin-1 (TSP-1), and angiostatin factor are already well studied in peripheral blood and bone marrow." (PMID 28727816, 2017). "Taken together, these results demonstrate that elotuzumab plus lenalidomide increases soluble TNF-α and IFN-γ levels and that TNF-α contributes to increased NK cell activation and myeloma cell killing." (PMID 25287778, 2015). "It has been reported, for example, in myeloma, to suppress angiogenic factors such as vascular endothelial growth factor (VEGF), and inflammatory genes such as TNF-alpha and IL-6." (PMID 20181085, 2010). "Furthermore, tumor necrosis factor-α (TNF-α) plays a dual role in MM, promoting B-cell proliferation while also inducing myeloma cell death." (PMID 41562677, 2026).
myeloma (continued). "The mechanism of action of lenalidomide in MM is not well understood but may relate to tumor necrosis factor (TNF)-alpha inhibition, downregulation of proinflammatory cytokines, direct cytotoxic effects on myeloma cells, and antiangiogenic activity." (PMID 39050339, 2024). "MDSC production of S100A9, a calcium-binding protein that promotes the release of TNF-α, IL-6, and IL-10 in autocrine pathway through TLR4 interaction, attracts myeloma cells in the TME and supports myeloma cell growth via the activation of the canonical NFκB pathway." (PMID 36726975, 2022). "Myeloma cells secrete a number of cytokines known to drive disease progression, one of which is TNF‐α.30, 31 Measurement of TNF‐α in the bone marrow plasma of myeloma‐bearing mice demonstrated a significant correlation with tumor burden, confirming an association with disease progression." (PMID 31886918, 2020). "Interestingly, binding studies revealed a straightforward correlation between cell surface TNFR1 expression in multiple myeloma cell lines and their sensitivity for MLN4924/TNF-induced cell death." (PMID 31406107, 2019). "Therefore, we investigated here the effect of TNF and MLN4924 on the viability of MM cell lines and primary myeloma cells." (PMID 31406107, 2019). "Thus, the sensitivity for TNF + MLN4924 treatment defines two subgroups of primary MM cells and mirrored in this regard the situation obtained with the human myeloma cell line panel." (PMID 31406107, 2019). "The combination of Elo with lenalidomide in co-cultures of peripheral blood mononuclear cells (PBMC) and myeloma cells also increased upregulation of NK cell activation marker, adhesion molecules, and cytokine production (IFN-γ, TNF-α, IL-2), as compared to either agent alone." (PMID 30455698, 2018). "Mutational activation of the non-canonical NFκB pathway modified TNF signaling to impart drug resistance in myeloma cells independent of the principal NFκB subunit RelA." (PMID 27641334, 2017). "TNF-α, IFN-γ, and IL-2 are important inflammatory cytokines that influence NK cell activation and may have direct cytotoxic effects on myeloma cells." (PMID 25287778, 2015). "In co-culture assays, TNF-α directly increased NK cell activation and myeloma cell death with elotuzumab or elotuzumab plus lenalidomide, and neutralizing TNF-α decreased NK cell activation and myeloma cell death with elotuzumab." (PMID 25287778, 2015). "TNF-α, but not IFN-γ, exerted direct dose-dependent anti-myeloma activity at doses that were in the range of soluble TNF-α levels (50–250 pg/mL) produced in the co-cultures." (PMID 25287778, 2015). "The neoangiogenesis evident in the bone marrow of subjects with myeloma is mediated by increased levels of basic fibroblast growth factor, vascular endothelial growth factor (VEGF), interleukin (IL)-lβ and tumour necrosis factor (TNF)-α." (PMID 19152712, 2009). "In multiple myeloma, osteoclast activation stimulates bone resorption through receptor activator of nuclear factor Κ B-ligand (RANKL), macrophage inflammatory proteins (MIP1α), IL-6, and tumor necrosis factor-α (TNF-α) pathways, with increased calcium release into the circulation." (PMID 39768494, 2024). "Interestingly, the analysis of secreted pro-inflammatory cytokines and effector molecules showed that TIM-3-, LAG-3-, and 2B4-disrupted TCRED T cells produce higher amounts of IL-2, TNFα, sFasL and perforin compared to TCRED-IRCOMP T cells when tested with the two different multiple myeloma models." (PMID 38510235, 2024). "This imbalance can be mediated directly by myeloma cells via the receptor activator of NF-B ligand (RANKL), hepatocyte growth factor (HGF) or interleukin (IL)-3, or indirectly via BMSC through the upregulation of RANKL and secretion of IL-6, IL-1β or tumor necrosis factor (TNF)-α." (PMID 36361677, 2022).
myeloma (continued). "IL-1b, TNF-a, IL-6, and IL-10 may contribute to osteopenia; IL-1b, TNF-a, and IL-6 may have a role in the activation of coagulation and hypermetabolism; IL-6 and IL-10 may be responsible for gammopathies and multiple myeloma." (PMID 36498496, 2022). "BZT also decreases adhesion of myeloma plasma cells to stromal cells and disrupts secretion of specific cytokines in the bone marrow microenvironment such as vascular endothelial growth factor (VEGF), insulin-like growth factor 1 (IGF-1), interleukin-6 (IL-6), and tumor necrosis factor-α (TNF-α)." (PMID 31979371, 2020). "Finally, myeloma cells lacking p100 owing to genetic aberrations produced a long-lasting pro-survival RelB response to brief TNF stimulation." (PMID 31134075, 2019). "Therefore we believe that our analysis of the regulation of the TNF network by CK2 is relevant to several different epithelial cancer types and may also be relevant to other malignancies such as myeloma." (PMID 26871292, 2016). "We also examined whether TNF-α or IFN-γ could exert anti-myeloma activity in the absence of effector cells." (PMID 25287778, 2015). "The combination enhanced myeloma cell killing by modulating NK cell function that coincided with the upregulation of adhesion and activation markers, including interleukin (IL)-2Rα expression, IL-2 production by CD3+CD56+ lymphocytes, and tumor necrosis factor (TNF)-α production." (PMID 25287778, 2015). "Since TNF-α has been shown to vary significantly phosphorylation of p65 at Ser 536 in the transactivation domain (TAD) compared to Thr 254, Ser 276, Ser 311, and Ser 529 in a variety of cell types, we chose to detect phosphorylation of p65 at Ser 536 in myeloma cells." (PMID 22384180, 2012). "Bortezomib decreases the adhesion of the myeloma plasma cell to stromal cells, which increases sensitivity to apoptosis, as well as interrupts prosurvival paracrine and autocrine cytokine loops in the bone marrow microenvironment mediated by IL-6, IGF1, VEGF and TNFα." (PMID 15655538, 2005). "The immunomodulatory drugs (IMiDs) are 50 000 times more potent at inhibiting TNF secretion, more potent inducers of T-cell proliferation with IFN and IL-2 secretion, and inhibitors of IL-1B and IL-6 secretion, and in in vitro studies demonstrate an increased myeloma cell kill." (PMID 15655538, 2005). "The addition of a TNF‐α‐neutralizing antibody restored both adiponectin expression levels and BMAd number; however, interestingly, viability was not altered by blockade of TNF‐α, suggesting additional mechanisms may contribute to the effect of BMAds on myeloma cell viability." (PMID 31886918, 2020). "We observed that TNF-α induced p65 phosphorylation within 30 minutes, and significantly suppressed the phosphorylation of p65 with the time-dependent in overall interval times, importantly As2O3 could further suppressed p65 phosphorylation in response to TNF-α treatment in myeloma cells." (PMID 22384180, 2012). "In multiple myeloma, TNF-α generated by tumor cells is augmented and amplifies apoptosis of osteocytes, while neutralization of TNF-α failed to completely reverse this effect." (PMID 33308247, 2020). "We showed that TNF-α, but not IFN-γ, exerted direct anti-myeloma cell activity, consistent with previous studies." (PMID 25287778, 2015). "Neutralization of TNF-α, but not IFN-γ, significantly inhibited myeloma cell killing and NK cell activation in elotuzumab, as well as elotuzumab plus lenalidomide co-cultures." (PMID 25287778, 2015). "In moribund myeloma-bearing (MB) mice, we previously showed that splenic PD-1+ T cells stimulated with anti-CD3 exhibit an altered cytokine profile (i.e., secreted less IL-2, IFN-γ and TNF-α) as compared to PD-1− T cells or T cells from non-MB mice." (PMID 28642819, 2017).
congestive heart failure (185 papers, 2004 to 2026). Failure of the heart to pump a sufficient amount of blood to meet the needs of the body tissues, resulting in tissue congestion and edema. "Patients with congestive heart failure often show elevated circulating TNF-α, which is associated with increasingly severe myocardial dilatation and fibrosis, and have a worse prognosis due to having more advanced diseases." (PMID 41590667, 2026). "Congestive heart failure is associated with an elevated production of inflammatory cytokines, specifically TNF-α and IL-6." (PMID 40364122, 2025). "TNF‐α is associated with impaired systolic and diastolic function, as well as adverse cardiac remodelling in chronic heart failure." (PMID 38509725, 2024). "Cats with congestive heart failure caused by cardiomyopathies including HCM have demonstrated increased plasma concentrations of tumor necrosis factor alpha (TNF-α) and serum amyloid A concentrations." (PMID 35359679, 2022). "It had been shown that TNF-α led to sarcomeric dysfunction and remodeling by causing autophagy defects and enhancing myofibril degradation in congestive heart failure." (PMID 34925026, 2021). "Chronic heart failure is also associated with increased levels of circulating pro-inflammatory cytokines, i.e., tumor necrosis factor-α (TNF-α), interleukin-1 (IL-1), and interleukin-6 (IL-6)." (PMID 29562608, 2018). "Elevated levels of circulating TNF-α and IL-6 are associated with the development of congestive heart failure and mortality in congestive heart failure patients." (PMID 26266925, 2014). "In the previous study, TNF-α and IL-1β have been implicated in the pathogenesis of myocardial dysfunction in chronic heart failure, and are suspected to mediate LV remodeling." (PMID 25250773, 2014). "Both HIV-associated cardiomyopathy and chronic heart failure have been associated with activation of the immune system leading to the pathogenic overproduction of several proinflammatory cytokines, including TNF-α, IL-1β, IL-6 and IL-18." (PMID 21203448, 2010). "An elevated nutrient–inflammation interaction score, integrating plasma TNF-α with the geriatric nutritional risk index, independently predicts incident cancer in older adults with chronic heart failure and enhances risk discrimination beyond conventional factors." (PMID 41473193, 2025). "The upregulation of TNF-α levels in the left ventricle, in turn, reveals the existence of a link between a process of local inflammation caused by Ang II and subsequent fibrosis and congestive heart failure." (PMID 39596537, 2024). "DOX can cause cardiotoxicity, cardiomyopathy, and congestive heart failure through inflammatory mechanisms and an increase in IL-8, NFκB, TNFα, monocyte chemotactic protein-1 (MCP-1), and Doxorubicin-mediated activation of NFκB and inflammatory cytokines by the effect of DOX through HMGB1." (PMID 35340325, 2022). "While biological agents (e.g., anti-TNF monoclonal antibodies) emerge as an alternative option, they have also been held by secondary responses that include the risk of hypersensitivity, immunogenicity, infection, and congestive heart failure." (PMID 27293323, 2016). "Besides its immediate effects on the contractile performance of the myocardium, there is also good experimental evidence for a causal pathophysiological role of TNF-α for the progression of myocardial remodeling leading to chronic heart failure." (PMID 23740214, 2013). "For instance, TNF-α was found to be elevated in chronic heart failure (HF) and newly diagnosed HF patients." (PMID 40283676, 2025). "TNF-α overexpression directly leads to congestive heart failure while mediating the progression of CKD through apo-A4 expression via the TNF receptor and the 2-NF-κB pathway." (PMID 41325840, 2025). "The plasma metabolite ethyl salicylate was correlated positively with pro-inflammatory factors, including IL-6 and TNF-α, in elderly patients with chronic heart failure." (PMID 40121482, 2025).